BTK (Bruton tyrosine kinase)
Diseases named in the same sentence as BTK in open-access papers (continued):
Sharing a sentence is not in itself a finding about the gene and the disease.
BTK also shares sentences with these, for which no sentence is quoted: genetic disorder (8 papers); Allergy (7); autoimmune hemolytic anemia (4); common variable immunodeficiency (4); bladder cancer (3); cardiac arrhythmia (3); myelodysplastic syndrome (3); respiratory failure (3); skin cancer (3); squamous cell carcinoma (3); Wiskott-Aldrich syndrome (3); X-linked disease (3); eosinophilia (2); haemorrhage (2); hemophagocytic lymphohistiocytosis (2); hypogammaglobulinemia (2); lymphopenia (2); mucormycosis (2); myelofibrosis (2); myeloproliferative diseases (2); myocardial infarction (2); periodontal disease (2); Pleural effusion (2); Sm (2); T-cell leukemia (2); urinary tract infection (2); vasculitis (2); X-linked hyper-IgM syndrome (2); X-linked lymphoproliferative disease (2); 22q11.2 deletion syndrome (1).
A further 116 diseases each share a sentence with BTK in 1 paper.